MIR2052HG (MIR2052 host gene)
Gene: Long non-coding RNA gene on chromosome 8 (74,599,757 to 74,823,313, forward strand). Ensembl gene ENSG00000254349.
Diseases named in the same sentence as MIR2052HG in open-access papers:
MIR2052HG is named in the same sentence as 2 diseases in open-access papers, as found by Europe PMC text mining. Sharing a sentence is not in itself a finding about the gene and the disease. The quoted sentences say what the papers report.
breast carcinoma (1 paper, 2019). "Downregulation of MIR2052HG reduced ERα-positive breast cancer cell growth." (PMID 30944027, 2019). "As a direct target of MIR2052HG, LMTK3 regulated downstream PKC/AKT/FOXO3 and PKC/MAPK/RSK1/ERα signaling, therefore regulating ERα-positive breast cancer growth and AI response." (PMID 30944027, 2019).
cancer (2 papers, 2019 to 2025). A tumor composed of atypical neoplastic, often pleomorphic cells that invade other tissues. "At mechanistic level, we found that MIR2052HG positively regulated ERα at both mRNA and protein levels via LMTK3 to maintain the cancer cell growth." (PMID 30944027, 2019).